IL6 (interleukin 6)
Diseases named in the same sentence as IL6 in open-access papers (continued):
Sharing a sentence is not in itself a finding about the gene and the disease.
inflammation (continued). "A variety of cytokines, including IL-6, IL-8, IL-10 and ICAM-1, are considered to participate in lung inflammation, which is closely related to the development of BPD." (PMID 23935746, 2013). "In contrast, high dose IT IL-6 resulted in marked anti-inflammatory effects as judged by reduced BAL fluid cytokines (IL-6, CXCL1, TNF-α), lung inflammation (IL-6, CXCL1, IL-1β), and serum CXCL1." (PMID 23667439, 2013). "The IRP is, however, also characterized by an increase of pro-inflammatory cytokines (such as IL-6 and TNF-α) and a low grade, chronic inflammation." (PMID 20886083, 2010). "Previous data from a mouse model of allergic and IL-6 induced lung inflammation have shown dissociation between intensity of AHR and the lung inflammation." (PMID 15932644, 2005). "Chronic intestinal inflammation in IBD is driven in part by elevated pro-inflammatory cytokines such as TNF-α, IL-6, IL-17, IL-1β, and IFN-γ, which collectively promote leukocyte recruitment, amplify epithelial injury, and sustain a feed-forward inflammatory loop." (PMID 41333470, 2025). "Hypoxia stimulates reactive oxygen species (ROS) production and calcium release, activating inflammatory pathways (e.g., AP-1, STAT3, and MAPK) and increasing cytokines, such as IL-6, TNF-α, and IL-1, thereby exacerbating airway inflammation and lung ischemia–reperfusion injury." (PMID 41408473, 2025). "Studies have shown that persistent short sleep can induce low-grade systemic inflammation, increasing levels of C-reactive protein, IL-6, and TNF-α in the blood, thereby exacerbating chronic systemic inflammation, particularly in older and frail individuals, and promoting the onset of frailty." (PMID 41468459, 2025). "The analysis of mRNA expression revealed that TNF-α, IL-1β, and IL-6 levels were higher in the colons of the HFV group, when compared with those of the NDV group, indicating high-fat/calorie diet-induced gut inflammation." (PMID 40284250, 2025). "Notably, IL-6, CCL2, GM-CSF, and KC/IL-8 have been identified as key biomarkers of ALI and ARDS, owing to their critical roles in the pathogenesis of pulmonary inflammation, endothelial and epithelial injury, and immune cell recruitment." (PMID 41316271, 2025). "Curcumin and its derivatives exert their effects by inhibiting the NF-κB signaling pathway, which downregulates pro-inflammatory factors such as COX-2, JNK, PI3K, and AP-1, thereby reducing the secretion of pro-inflammatory mediators like IL-6, IL-1β, TNF-α, and alleviating joint inflammation." (PMID 40806131, 2025). "LPS can cross the intestinal barrier into the body circulation and reach the lungs, where it exacerbates COPD lung inflammation through the toll-like receptor 4/ nuclear transcription factor-κB (TLR4/ NF-κB) signaling pathway mediating the production of IL-1β, IL-6, IL-17 TNF-α." (PMID 40098933, 2025). "In addition, the overexpression of pro-inflammatory cytokines, such as IL-6, TNF-α, and IL-1β, from the macrophages is further involved in the upregulation of inflammatory reactions resulting in inflammation-related diseases." (PMID 39200485, 2024). "Additionally, ZDF diabetic animals showed pancreatic inflammation evidenced by increased levels of the inflammatory markers TNF-α, IL-6, and p-p65." (PMID 38257166, 2024). "Combined with the correlation analysis that PIEZO1 expression was positively correlated with inflammatory mediators, IL-1β, TNF-α, and IL-6, it is speculated that PIEZO1 might play a vital role in the development of pulpal inflammation." (PMID 38627713, 2024). "Numerous studies have indicated that over-expressions of cytokines such as IL-1, IL-6, and TNF-α may promote liver inflammation during chronic liver injury." (PMID 38136147, 2023).
inflammation (continued). "Studies have shown that drugs can reduce the levels of IL-6 and IL-1β by inhibiting STAT3 expression, thereby ameliorating liver inflammation; targeting the STAT3 signaling pathway is considered an attractive therapeutic strategy for the development of anti-inflammatory drugs." (PMID 37165407, 2023). "In our study, YCF treatment significantly inhibited pulmonary inflammation in silica-exposed rats, by reducing inflammatory cell infiltration, and decreasing the secretion of inflammatory chemokines, including TNF-α, IL-1β, and IL-6." (PMID 37381044, 2023). "The authors concluded that up-regulated IL-33 levels may facilitate lung inflammation by promoting the production of a range of innate pro-inflammatory cytokines, including TNF-α, IL-1β, IL-6, IL-12, IL-23." (PMID 36875710, 2023). "Studies have shown that the expression of pro-inflammatory cytokines (such as IL-1β, IL-6, TNF-α, etc.)is significantly increased during intestinal inflammation, leading to a significant increase in intestinal epithelial tight-junction barrier permeability as a result of multiple effects." (PMID 37240380, 2023). "Significant changes in inflammatory and endothelium-specific variables IL-1β, IL-6, TNFα, oxLDL, H2O2, NO, 3-nitrotyrosine, and endothelial progenitor cells (OR 7.61, 95% CI 2.56–29.05, p < 0.0001), confirmed their interplay in vascular inflammation." (PMID 36362055, 2022). "Over the course of 7 days, DSS-treated TRPV1-hM4Di mice developed intestinal inflammation characterized by a slight decrease in the body weight, increase in macroscopic damages and production of pro-inflammatory cytokines TNF-α, IL1-β, and IL-6." (PMID 34954381, 2022). "The anti-inflammatory abilities of CS extract were also determined in HFD mice and we found a significant increase in IL-6 and TNF-α levels of serum and liver in the HFD group in comparison to the control group indicating an occurrence of systemic chronic inflammation (p < 0.05)." (PMID 35978956, 2022). "Pirfenidone ameliorates lipopolysaccharide-induced pulmonary inflammation and fibrosis by blocking NLRP3 inflammasome activation and reducing lung injury induced by COVID-19 pneumonia; it also reduces plasmatic and pulmonary IL-6 concentration." (PMID 36010377, 2022). "Therefore, IL-6 and TNF-α are considered to be important mediators of chronic intestinal inflammation." (PMID 35321324, 2022). "First, inhaled particles may provoke pulmonary inflammation, leading to systemic inflammation, including elevated levels of tumor necrosis factor-a (TNF-a), interleukin-6 (IL-6), plasminogen activator inhibitor-1, and oxidative stress." (PMID 35462847, 2022). "For the investigation of the effect of GFDHP on airway inflammation, the counts of inflammatory cells (including total cells, white blood cells (WBC), lymphocytes, and neutrophils) and the levels of cytokines (IL-1β and IL-6) in BALF were detected." (PMID 34777538, 2021). "Lung inflammation was more severe with the whole-body CS exposure system as shown by an enhanced lymphoid presence in BAL, lymph nodes and the upregulation of cytokine (IL-6) and chemokine (CXCL1) mRNA expression in the lung." (PMID 33731130, 2021). "Moreover, we also exhibited that the PO extract (100 and 200 mg/kg, p.o.)inhibited lung inflammation by downregulating TNF-α, IL-6, IL-β, TGF-β, and PGE2 levels and upregulating the expression level of IL-10." (PMID 34381307, 2021). "SIRS may lead to an acute lung inflammation known as post-perfusion lung syndrome, in which TNF-α, IL-6, IL-8, and IL-1β have a pivotal role." (PMID 33505996, 2020). "Interestingly, macrophage-specific Dpep2 deletion robustly aggravated CVB3-induced cardiac inflammation, evidenced by augmented expression of TNF-α, IL-6, and MCP-1 in heart tissue." (PMID 30899700, 2019). "Therefore, to further evaluate the effects of the EAFPg on lung inflammation, we measured the inflammatory markers TNF-α, IL1-β, and IL-6." (PMID 29675437, 2018).
inflammation (continued). "The inhibition of both IL-6 and KC/CXCL1 may be important in decreasing neutrophilic airway inflammation augmented by ambient PM." (PMID 29882826, 2018). "Collectively, the reductions in IL-6 and increases in IL-10 observed in the Caco-2/THP-1 model of intestinal inflammation containing SHIME suspensions suggest that the probiotics with digestive enzymes supplement affects the gut microbiome toward controlling inflammation." (PMID 30112118, 2018). "Short-lived STAT3-induction by IL-6 inadequately opposes RA-driven STAT5 induction resulting in suppression of Th17 differentiation in presence of IL-6 both in vitro and in the intestinal lamina propria during acute intestinal inflammation." (PMID 28408906, 2017). "After multivariate adjustment, IL-6 remained an independent predictor of LTI in our study, suggesting that the development of decreased muscle mass in CKD may be mediated by chronic inflammation." (PMID 28448447, 2017). "Activation of PPARγ can decrease endotoxemic-induced, lipopolysaccharide-induced, and hemorrhage-induced acute pulmonary inflammation and injury through inhibition of neutrophil accumulation, ICAM-1 expression, and proinflammatory cytokine (IL-6, IL-1β) production." (PMID 27556035, 2016). "The rats with SP presented with a shorter refractoriness, a higher incidence and duration of AF, an enhanced susceptibility to developing AF, increased mRNA levels of AF-related pro-inflammatory cytokines (IL-6, IL-1β and TGF-β1), as well as marked atrial inflammation and fibrosis." (PMID 25955429, 2015). "Interestingly, during joint inflammation, overexpression of CLEC5A/MDL-1 recruits inflammatory cells and induces the production of IL-1, IL-6, IL-17A, and TNF, contributing to cartilage damage and bone erosion." (PMID 26086874, 2015). "In order to investigate whether feeding a HFD for 16 weeks induces cardiac inflammation, protein expression of major pro-inflammatory cytokines was quantified as direct or indirect measure of TLR4 signaling (i.e., IL-6/TNF-α and SOCS-3, respectively)." (PMID 26539824, 2015). "SIRS was assessed by serum proinflammatory cytokines (TNF-α, IL-1β, CXCL1, IL-6), ALI was assessed by lung inflammation (lung myeloperoxidase [MPO] activity), and AKI was assessed by serum creatinine, BUN, and glomerular filtration rate (GFR) (by FITC-labeled inulin clearance) at 4 hours." (PMID 24265742, 2013). "Thus, through its inhibition of the IL-17-induced production of IL-6, GCP-2 and RANKL, IFN-γ can profoundly limit granulopoiesis, mobilisation of neutrophils, and bone destruction, which are all important in joint inflammation." (PMID 19686583, 2009). "Using TLR2- and TLR4-deficient mice, we further demonstrated that PM2.5-induced increases in BAL cell counts, ROS, IL-6, and TNF-α were partially attenuated in TLR4 knockout mice, indicating a contributory but not exclusive role for TLR4 signaling in PM2.5-driven pulmonary inflammation." (PMID 41596147, 2026). "Moreover, plasma levels of IL-17 and IL-6 were significantly reduced in LY294002 treated mice relative to that in untreated mice, further suggesting that the anti-inflammatory effects of LY294002 on neutrophilic airway inflammation." (PMID 38811424, 2024). "Chronic inflammation, defined as a prolonged, low-grade inflammatory response that persists over time, is characterized by elevated levels of circulating pro-inflammatory markers such as C-reactive protein (CRP), interleukin-6 (IL-6), and tumor necrosis factor-alpha (TNF-α)." (PMID 39519418, 2024). "Inflammation mediators such as NO, PGE2, interleukin 6 (IL-6), tumor necrosis factor-alpha (TNF-α), and interleukin 8 (IL-8) are some examples of cell signaling molecules that promote prolonged inflammation, and if uncontrolled can result in chronic inflammation." (PMID 35056836, 2022).
inflammation (continued). "Moreover, the concomitant thoracic trauma induced pulmonary inflammation, indicated by lung damage, increased inflammatory mediators in the BAL fluids, including IL-6, IL-5, eotaxin, MCP-3, and MCP-1, and increased neutrophil infiltration into the lungs in mast cell-competent mice." (PMID 35558068, 2022). "Therefore, we thought that SG inhibited IL-6 production of inflammatory BEAS-2B cells, which could contribute to attenuate pulmonary inflammation in asthmatic mice." (PMID 35682783, 2022). "The subacute phase of OVA-induced lung inflammation evaluated 4 weeks after the last challenge is characterized by the decrease in the number of leukocytes and granulocytes as well as IL-6 in the BAL fluid, but not to healthy levels, while TNF-α reached the values of healthy animals." (PMID 35625754, 2022). "The reduced bacterial burden observed in mice treated with LPS was associated to a reduced pulmonary inflammation as shown by a lower neutrophil number in BALF and lungs and a decreased mRNA expression of the pro-inflammatory genes Tnfα and Il-6, but not Il-1β and Cxcl1, in lungs." (PMID 35493510, 2022). "Since COX2 is known to be induced in endothelial cells by inflammatory stimuli and shear stress, and is involved in the development of vascular inflammation, the subsequent decrease of COX2 and IL-6 after ACT-03 treatment might be an indication of the dampened activation state of these cells." (PMID 36140216, 2022). "Inhibitors of phospholipase D, which specifically cleave phosphatidylcholine (PC) into phosphatidic acid (PA) and choline, could significantly reduce the production of IL-6 and IL-8 in RA-FLS, demonstrating the importance of phospholipid metabolism in synovial inflammation." (PMID 36144243, 2022). "Three days of exposure to Pb induced severe lung inflammation as evidenced by (a) increased the gene expression of several inflammatory cytokines and mediators such as IL-4, IL-10, iNOS, TNF-α, and TGF-α and (b) inhibited the gene expression of anti-inflammatory markers such as IL-6 and IL-8." (PMID 35482242, 2022). "GM-CSF and IL-6 can promote the activation and maturation of dendritic cells, macrophages, and T cells, providing an additional mechanism by which lung-expressed LIGHT together with IL-13 could perpetuate lung inflammation." (PMID 29616048, 2018). "Moreover, the elevated expression of ICAM-1, IL-6, and IL-8 in tEV-treated HUVEC, suggest that EV may translocate these pro-inflammatory mediators and promote vascular endothelial inflammation." (PMID 30131806, 2018). "Next, we investigated the role of ROS in PMs-induced pulmonary inflammation, pre-administration of NAC (3–5 mg/mouse) before intratracheal instillation of PMs (200–350 μg/mouse, 7 days) significantly attenuated PMs-induced ICAM-1 and IL-6 expression in lung tissues by immunohistochemical staining." (PMID 29329563, 2018). "Furthermore, adipose IL-6 and TNF-α mRNA levels were significantly higher in SERT−/− adipose compared with WT, indicating that lipid accumulation in SERT−/− mice stimulated adipose inflammation." (PMID 28442777, 2017). "Finally, GLP induced p38 phosphorylation and IL-6 production in lung epithelial cells, and this effect was reversed by the selective p38 inhibitor SB203580, which addresses a key role of p38 in GLP-induced lung inflammation." (PMID 25265888, 2014). "Thus, LPS on the particles may have an important role in inducing neutrophilic airway inflammation via MIP-2/CXCL2 and IL-6 elevation." (PMID 25386753, 2014). "For example, pro‐inflammatory mediators including IL‐1β, IL‐6, and TNF‐α promote a reduction in the NAD+/NADH ratio, leading to an impairment in mitochondrial biogenesis, while mitochondrial dysfunction may induce cardiac inflammation via the release of mitochondrial DNA or formation of ROS." (PMID 37365150, 2023).
inflammation (continued). "Therefore, initially we hypothesized that after the development of chronic allergic lung inflammation by long-term administration of intranasal HDM, mice would exhibit increased serum IL-6 and TNF-α concentrations, which had been observed in other systemic inflammation models." (PMID 36045388, 2022). "Furthermore, we analyzed EV-depleted conditioned medium of LPS-stimulated macrophages in cardiomyocyte stimulation, which resulted in significantly elevated IL-6 protein concentrations, thus supporting our finding that proinflammatory macrophage-derived EVs do not mediate cardiac inflammation." (PMID 36555168, 2022). "In addition to pulmonary inflammation, there is also systemic inflammation with increased levels of fibrinogen, C-reactive protein (CRP), serum amyloid A (SAA), and pro-inflammatory cytokines tumor necrosis factor-alpha (TNF-α), interleukin-6 (IL-6), and IL-8 in the serum." (PMID 34681202, 2021). "In contrast, Ly6C‐ cDCs exert minimal effects on both T cell differentiation and ALI development due to their low intrinsic expression of Il‐6 and Il‐1β, although the MEK/ERK/NF‐κB signaling is not inactivated during pulmonary inflammation." (PMID 40789072, 2025). "Indeed, a recent study showed the non-involvement of IL-1β in synovial inflammation and cartilage destruction during collagenase-induced OA and it was suggested that other inflammatory mediators (possibly the alarmins, IL-6 and IL-17) could be responsible for the joint damage." (PMID 33193305, 2020). "At week 12, the GMA-SS exposure induced pulmonary inflammation in both strains, without consistent changes in markers of systemic inflammation (CRP, MCP-1, IL-6 and TNFα)." (PMID 31924220, 2020). "While we have not analyzed the molecular mechanism leading to heart inflammation during MS, experimental data has shown that Toll-like receptor 4 (TLR4) stimulation by fatty acids promotes TNF-α, IL-6, and IL-1β gene expression." (PMID 29201273, 2017).